RN7SL392P (RNA, 7SL, cytoplasmic 392, pseudogene)
Gene: Miscellaneous RNA gene on chromosome 1 (67,656,831 to 67,657,129, reverse strand). Ensembl gene ENSG00000242482.
Homologues: Orthologues: chimpanzee Metazoa_SRP (99% identical), macaque Metazoa_SRP (91% identical). Paralogues in human: RN7SL1 (76% identical), RN7SL2 (76% identical), Metazoa_SRP (76% identical), RN7SL627P (76% identical), RN7SL88P (76% identical), Metazoa_SRP (75% identical), RN7SL127P (75% identical), RN7SL3 (75% identical), RN7SL357P (75% identical), RN7SL448P (75% identical), RN7SL342P (75% identical), RN7SL566P (75% identical), and 700 more.